PRPH2 (peripherin 2)
Diseases named in the same sentence as PRPH2 in open-access papers (continued):
Sharing a sentence is not in itself a finding about the gene and the disease.
cone dystrophy (3 papers, 2017 to 2024). An inherited ocular disorder characterized by the loss of cone cells, the photoreceptors responsible for both central and color vision. "Thus, both diseases could be categorized as mainly cone dystrophies, at least when caused by the p.Arg195Leu PRPH2 mutation." (PMID 33925984, 2021).
glaucoma (3 papers, 2021 to 2023). Increased pressure in the eyeball due to obstruction of the outflow of aqueous humor. "Therefore, we inferred that ACG was an accompanying symptom of RP, in this case, and that the PRPH2 mutation might be related to the co-occurrence of glaucoma and RP." (PMID 34399712, 2021). "However, the potential association between PRPH2 and glaucoma has not been reported in the literature." (PMID 34399712, 2021). "However, the genetic correlation between PRPH2 and glaucoma has not been reported yet." (PMID 34399712, 2021).
central serous chorioretinopathy (2 papers, 2022 to 2023). "A list of differential diagnoses includes SFD, pattern dystrophy (associated gene PRPH2), or other dominantly inherited macular dystrophies, including late stage Best disease (BEST1), and central serous retinopathy with secondary CNV." (PMID 36421778, 2022).
Chorioretinal atrophy (2 papers, 2023 to 2025). Atrophy (wasting) of the choroid and retinal layers of the fundus. "It is involved in the onset of several IRDs such as Pattern Dystrophy, Extensive Chorioretinal Atrophy, Pattern Dystrophy simulating Fundus Flavimaculatus, and autosomal-dominant RP, highlighting the considerable phenotypic heterogeneity associated with PRPH2." (PMID 40722607, 2025).
night blindness (2 papers, 2015 to 2023). Inability to see clearly in dim light. "In a previous study, the p.(Arg172Trp) mutation in PRPH2 was found to segregate in two independent families with affected members showing symptoms with blurred central vision and photophobia, while no complain of night blindness or restricted peripheral vision." (PMID 26667666, 2015).
Photophobia (2 papers, 2015 to 2021). Excessive sensitivity to light with the sensation of discomfort or pain in the eyes due to exposure to bright light. "Patients of the PRPH2 cohort did not report photophobia and dyschromatopsia, but this is very likely due to the small size of this cohort." (PMID 34073554, 2021).
Adult onset (1 paper, 2024). Onset of disease manifestations in adulthood, defined here as at the age of 16 years or later. "Moshfeghi and colleagues reported sub-foveal CNVM in three patients with adult-onset foveomacular dystrophy caused by RDS/PRPH2 gene pathogenic variants." (PMID 39610584, 2024).
amyotrophic lateral sclerosis (1 paper, 2015). Amyotrophic lateral sclerosis (ALS) is a neurodegenerative disease characterized by progressive muscular paralysis reflecting degeneration of motor neurons in the primary motor cortex, corticospinal tracts, brainstem and spinal cord. "NF-L binds to Mapk12 (mitogen-activated protein kinase 12), Mapk13, Mapk14, Nefh (neurofilament), Nefm, Prph (peripherin) and Prph2 which are involved in pathway associated to Amyotrophic Lateral Sclerosis (ALS)." (PMID 25561935, 2015).
autoimmune uveitis (1 paper, 2015). An autoimmune form of uveitis (disease). "However, until now, there was no information about peripherin 2 expression in RPE and whether expression changes of peripherin 2 were associated with autoimmune uveitis." (PMID 25629227, 2015).
autosomal dominant Stargardt-like macular dystrophy (1 paper, 2021). "However, high qAF levels were also observed in PRPH2-associated autosomal dominant Stargardt-like macular dystrophy, limiting its clinical relevance in the differential diagnosis of Stargardt and Stargardt-like macular dystrophies." (PMID 34073554, 2021). "The onset of clinical symptoms in PRPH2-associated autosomal dominant Stargardt-like macular dystrophy was reported to start later in life (≥50 years old), which could have allowed to distinguish them from the ABCA4 and ELOVL4 patients." (PMID 34073554, 2021).
choroidal neovascularization (1 paper, 2021). An eye disorder described by the growth of new blood vessels that originate from the choroid through a break in the Bruch membrane into the sub–retinal pigment epithelium (sub-RPE) or subretinal space. "Moreover, the PRPH2 p.(Tyr141Cys) variant can cause choroidal neovascularization in older patients." (PMID 34073554, 2021).
uveitis (1 paper, 2015). An inflammatory process affecting a part of or the entire uvea. "Most closely to our findings that peripherin 2 expression is downregulated in uveitis, the nmf193 mutant mouse model, exhibiting a single base change in the peripherin 2 gene, showed the downregulation of peripherin 2 in photoreceptor outer segments." (PMID 25629227, 2015).
retinopathy (17 papers, 2012 to 2025). "PRPH2 retinopathies are associated with an autosomal dominant inheritance pattern, and incomplete penetrance has been described, as well as significant interfamilial and intrafamilial phenotypic variability." (PMID 41009962, 2025). "Another variant with pathogenic effect is c.612C>G (p.Tyr204Ter), one of the most commonly reported truncating variants associated with PRPH2-related retinopathy." (PMID 40722607, 2025). "In conclusion, this study systematically researched PRPH2-associated retinopathy involving variant features, the clinical spectrum, and genotype–phenotype correlations." (PMID 37047703, 2023). "The high genetic and phenotypic heterogeneity of PRPH2-associated retinopathy undoubtedly increases the difficulty of assessing individual PRPH2 variants." (PMID 37047703, 2023). "Clinical spectrum and genotype–phenotype correlation analyses of PRPH2 have been mostly carried out in Caucasian cohorts; PRPH2-associated retinopathy has been rarely studied in Asian cohorts, particularly in Chinese cohorts." (PMID 37047703, 2023). "By December 2022, a total of 1013 families were reported to have PRPH2-associated retinopathy, and phenotypic variability in affected family members was observed in 40 families." (PMID 37047703, 2023). "Additionally, fusion of the ellipsoid and interdigitation zones resulted in a distinctive thickened second band on OCT, characteristic of PRPH2-associated retinopathy." (PMID 39023660, 2024). "PRPH2-associated retinopathies are most often inherited as an autosomal dominant trait." (PMID 37047703, 2023). "Even so, the genotype–phenotype correlation of PRPH2-associated retinopathy remains unclear, and the diagnosis, prognosis, and genetic counseling of variants in PRPH2 in the clinic are still difficult, especially for those ophthalmologists without extensive knowledge of this gene." (PMID 37047703, 2023). "The one patient with RP in our cohort reported the earliest symptom onset, which supports previous findings that RP patients manifest symptoms earlier, within the third-fifth decade, compared to other PRPH2 retinopathy phenotypes." (PMID 41009962, 2025). "ABCA4 and RPE65 have also been proposed as genetic modifiers that result in a more severe phenotype in PRPH2 retinopathy." (PMID 41009962, 2025). "Abnormal ERG responses have been reported in 78.2–92% of PRPH2 retinopathy patients, and cone and rod dysfunction has been reported in 50–68% of patients with a PSPD phenotype." (PMID 41009962, 2025). "Our findings highlight the significant phenotypic variability and complex nature of this condition and contribute valuable insights to the current understanding of PRPH2 retinopathy." (PMID 41009962, 2025). "These new data add to the previous literature, further enhancing our understanding of PRPH2 retinopathies and the potential selection of patients when appropriate gene-targeted therapies become available." (PMID 41009962, 2025). "This study provides a comprehensive analysis of genotype–phenotype correlations in PRPH2 retinopathy from a cohort of 36 patients from the Oxford Eye Hospital." (PMID 41009962, 2025). "A total of 36 patients (14 male, 22 female) with PRPH2 retinopathy were identified from 33 unrelated families." (PMID 41009962, 2025). "FAF imaging was highly valuable in delineating the different PRPH2 retinopathy phenotypes, consistent with previous reports." (PMID 41009962, 2025). "In conclusion, this study provides a comprehensive analysis of PRPH2 retinopathies in a small cohort." (PMID 41009962, 2025). "Among these pieQTLs, 27 are associated with retinopathies, including 3 that interact with their own eGene promoter (MYO7A, MERTK and PRPH2 genes)." (PMID 36207300, 2022).
retinopathy (continued). "Furthermore, pseudodominant families are frequent inABCA4-associated retinopathy due to high allelic load ofABCA4 variants in the general population and late onset diseaseexpression due to reduced penetrance of variants in both PRPH2 andABCA4 is well documented." (PMID 32278709, 2020). "Genes such as PRPH2 and PROM1 caused five and four different types of retinopathies, respectively, with predominant autosomal dominant traits for the PRPH2 gene and autosomal recessive traits for the PROM1 gene." (PMID 30374144, 2018). "The significant phenotypic variability in PRPH2 retinopathy highlights the importance of furthering our understanding of PRPH2 function in rod and cone photoreceptors through cellular and animal models, as well as natural-history studies in well-characterised patient cohorts." (PMID 41009962, 2025). "Moreover, the effect of environmental factors on the phenotype remains to be explored as their role is unknown in PRPH2 retinopathy." (PMID 41009962, 2025). "These foci had a particularly prominent appearance and often appeared to extend through multiple retinal layers—a feature that, to our knowledge, has not been specifically described in PRPH2 retinopathy." (PMID 41009962, 2025). "Similar to recent studies (e.g., multicenter PROGSTAR study), the diagnosis of ABCA4-related retinopathy was based on a compatible phenotype and the presence of at least one disease-causing mutation in ABCA4 as well as the absence of mutations in Peripherin-2 (PRPH2)." (PMID 32751377, 2020).
PRPH2 also shares sentences with these, for which no sentence is quoted: choroideremia (3 papers); retinitis punctata albescens (3); age-related macular degeneration (2); Bull's eye maculopathy (2); infection (2); retinoblastoma (2); tumor (2); achromatopsia (1); Alzheimer disease (1); angle-closure glaucoma (1); Anxiety (1); Ataxia (1); Best vitelliform macular dystrophy (1); bestrophinopathy (1); cancer (1); ciliopathies (1); Cognitive impairment (1); concentric annular macular dystrophy (1); deafness (1); diabetic retinopathy (1); Dyschromatopsia (1); gastric cancer (1); inherited macular dystrophies (1); Leber hereditary optic neuropathy (1); lung carcinoma (1); macular abnormalities (1); macular coloboma (1); macular edema (1); myopia (1); primary open angle glaucoma (1).
A further 8 diseases each share a sentence with PRPH2 in 1 paper.